ARL17B (ARF like GTPase 17B)
Description:
Putative small GTP-binding protein cycling between an inactive GDP-bound and an active GTP-bound form.
Synonyms: ARL17
Gene: Protein-coding gene on chromosome 17 (46,274,184 to 46,361,766, reverse strand). Ensembl gene ENSG00000228696.
Subcellular location (Human Protein Atlas): Nucleoplasm
Gene Ontology:
Molecular function: GTP binding; GTPase activity
Biological process: intracellular protein transport
Cellular component: nucleoplasm; plasma membrane
Homologues: Orthologues: dog ARL17A (44% identical), mouse Arf2 (44% identical), rat Arf1 (44% identical), Caenorhabditis elegans arf-1 (42% identical), Drosophila melanogaster Arf1 (42% identical), zebrafish arf2a (42% identical). Paralogues in human: ARL17A (100% identical), ARF1 (42% identical), ARF3 (42% identical), ARF4 (34% identical), ARF5 (34% identical), ARF6 (31% identical), ARL1 (29% identical), TRIM23 (28% identical), ARL4A (25% identical), ARL3 (24% identical), ARL4C (24% identical), ARL5B (23% identical), and 18 more.
Diseases named in the same sentence as ARL17B in open-access papers:
ARL17B is named in the same sentence as 15 diseases in open-access papers, as found by Europe PMC text mining. Sharing a sentence is not in itself a finding about the gene and the disease. The quoted sentences say what the papers report.
schizophrenia (2 papers, 2024 to 2025). A major psychotic disorder characterized by abnormalities in the perception or expression of reality. "ARL17B is implicated in schizophrenia, TPGS2 is found in the microtubule gene ontology term, and PRKAG2 is part of 4 pathways (AMPK signaling pathway, Lysine degradation, Cholinergic synapse, GnRH secretion) as well as the protein serine/threonine kinase activity gene ontology term." (PMID 38532526, 2024). "Furthermore, the DA population in schizophrenia had decreased expression of genes associated with the GO term ‘GTPase activity’, such as Ras-related protein Rab-27B (RAB27B), and ADP ribosylation factor (ARL17B)." (PMID 39397771, 2025).
breast carcinoma (1 paper, 2024). "We found that the e2QTL for ARL17B upon UVC and RPS18 upon HC exposure represent GWAS risk variants for breast cancer (r2 = 0.91, r2 = 1), both exhibiting reduced expression in carriers of the risk alleles." (PMID 39623312, 2024). "In addition, context specific regulatory effects for ARL17B and RPS18 were found to be associated with breast cancer." (PMID 39623312, 2024).
medulloblastoma (1 paper, 2022). A malignant, invasive embryonal neoplasm arising from the cerebellum. "For the last selected circular fusion in medulloblastoma, the ARL17B--KANSL1, it should be noted that the coding sequences of ARL17A (NM_001113738.2) and ARL17B (NM_001039083.5), including the exon 3 at the fusion, are identical." (PMID 35804907, 2022).
prostate carcinoma (1 paper, 2022). A carcinoma that arises from epithelial cells of the prostate gland. "There were no previous descriptions for the fusions NAIP:OCLN, PDE1C:DNAJC6, KANSL1:ARL17B, FOXP2:CREM, and AHSA1:DLG3 in the context of prostate cancer." (PMID 35625354, 2022).
brain disorder (1 paper, 2023). A disease affecting the brain or part of the brain. "Indeed, we found that many GWAS lead SNPs in brain disorders are located near the 3′UTR of target genes, such as ARL17B." (PMID 36737438, 2023).
ARL17B also shares sentences with these, for which no sentence is quoted: cancer (2 papers); bone metastasis (1); chronic myelogenous leukemia (1); cognitive decline (1); COVID-19 (1); leukemia (1); lung carcinoma (1); multiple sclerosis (1); progressive supranuclear palsy (1); tumor (1).